RNA5-8SN1 (RNA, 5.8S ribosomal N1)
Synonyms: RNA5-8S4
Gene: Ribosomal RNA gene on chromosome 21 (8,439,823 to 8,439,975, forward strand). Ensembl gene ENSG00000278189.
Gene Ontology:
Molecular function: structural constituent of ribosome
Cellular component: ribosome
Homologues: Orthologues: guinea pig 5_8S_rRNA (100% identical), pig 5_8S_rRNA (100% identical), rabbit 5_8S_rRNA (100% identical), rat 5_8S_rRNA (100% identical), dog 5_8S_rRNA (88% identical). Paralogues in human: 5_8S_rRNA (100% identical), RNA5-8SN2 (100% identical), RNA5-8SN3 (100% identical), RNA5-8SN4 (100% identical), RNA5-8SN5 (100% identical), 5_8S_rRNA (90% identical), 5_8S_rRNA (87% identical), 5_8S_rRNA (86% identical).